JUNB (JunB proto-oncogene, AP-1 transcription factor subunit)
Diseases named in the same sentence as JUNB in open-access papers (continued):
Sharing a sentence is not in itself a finding about the gene and the disease.
tumor (continued). "In this study, our results showed that c-Jun and JunB are involved in the curcumin-induced apoptosis in THP1 cells, suggesting the tumor suppressor role of c-Jun and JunB in THP-1 cells." (PMID 22443687, 2012). "While a very low or negligible expression of cJun, JunB, JunD, cFos, FosB, Fra-1 and Fra-2 was observed in normal adjacent tissues, the majority of them showed significantly elevated expressions in tumor tissues." (PMID 19758438, 2009). "An explanation for this could either be an upregulation of JUNB under the course of the (neoadjuvant) treatment, or a survival advantage of tumor cells highly expressing JUNB." (PMID 40701988, 2025). "Patients with JUNB-positive HCCs near tumor nodules have a high potential for lung metastasis." (PMID 40253402, 2025). "Furthermore, elevated JUNB levels have been shown to enhance tumor growth and metastasis in mice by altering the TGF-β2-stimulated response from an antiproliferative to a pro-invasive one." (PMID 40612060, 2025). "As JUNB attenuated the expression of cJUN, we then assessed whether cJUNlow areas in this heterogeneous tumor model exhibited high JUNB expression." (PMID 39762215, 2025). "Although these types of findings may seem contradictory, in other cancer types (even of urological origin), similar roles for JUNB have been described, thus attributing to it both oncogenic and tumor-suppressing properties." (PMID 41020863, 2025). "Therefore, the phenomenon in which JUNB-positive HCC cells are abundantly present near the fibers surrounding the tumor in pathological specimens of subcutaneous tumors upon mixing epithelial HCC cells with Tig3-20 cells is convincing." (PMID 40253402, 2025). "In contrast, the C3 subpopulation, enriched in genes like HBB and JUNB, may contribute to oxidative stress regulation and cell cycle progression, suggesting a more mature, functionally active tumor cell." (PMID 40406148, 2025). "Agents targeting the interactions of JUN family members with other TFs, like the JUND-AR-targeting GWARJD10, may provide new tools against JUNB/D-mediated tumor progression and become part of novel targeted therapies of high specificity." (PMID 41020863, 2025). "In vivo, the combined therapy markedly reduced the expressions of SRC and JUNB in tumor tissues." (PMID 40599804, 2025). "Therefore, the present study suggests that NCAPD3-knockdown-induced differentially expressed genes (DEGs) such as CRNDE, EDN1, and JUNB can regulate cell and tumor invasion through EGFR and PLAUR." (PMID 38711992, 2024). "JUNB, which is also activated by JNK has been associated with growth limiting properties in PCa and its activation may explain the mechanism of JNK’s tumor-suppression." (PMID 38811984, 2024). "Similarly, MZ-1 also enhanced inhibition of tumor cell growth upon siRNA-mediated JUNB knockdown in various MM cell lines." (PMID 39160158, 2024). "Therefore, TME influences the expression of JunB in tumor cells, which plays a vital role in promoting BM angiogenesis during MM development." (PMID 37731821, 2023). "Aberrant upregulation of c-Jun, JunB and CD30 is a hallmark of tumor cells in HL and ALCL." (PMID 37731821, 2023). "This suggests that JunB may serve as a crucial regulator in the macrophage polarization within the tumor microenvironment (TME)." (PMID 37731821, 2023). "Nevertheless, the tumor blood and lymphatic vascular density and integrity were not influenced upon JunB deficiency." (PMID 37731821, 2023). "Intriguingly, the m6A demethylase FTO was found to preserve the transcription factors of bZIP family, including c-Jun, JunB and C/EBPβ, through its demethylation activity, thereby upregulating the expression of glycolytic genes in tumor cells and facilitating tumor progression." (PMID 37731821, 2023). "The bidirectional role of JunB in immune regulation is evident as its regulatory effects on neutrophils may exhibit reversibility in other inflammatory diseases and tumor states." (PMID 37731821, 2023).
tumor (continued). "Various studies have outlined the positive role of JunB in tumor invasion and progression." (PMID 37179352, 2023). "Furthermore, the observation that JunB modulates macrophage activity within the TME by transcriptionally regulating chemokine secretion from tumor cells provides valuable insight, as M2 macrophages infiltration exacerbates solid tumor progression." (PMID 37731821, 2023). "However, the pro-angiogenic role of JunB contributes to certain tumor progression, this will be addressed in the following." (PMID 37731821, 2023). "However, this immunosuppressive effect of JunB can facilitate immune evasion by tumor cells within the TME." (PMID 37731821, 2023). "However, JunB also has oncogenic characteristics, after induced by TGF-β, JunB can further mediate downstream genes involved in tumor invasion and progression." (PMID 37483616, 2023). "However, other studies have found that high JUNB expression in the tumor microenvironment can strongly inhibit distant tumor metastasis." (PMID 37240946, 2023). "In vivo xenograft tumor results demonstrated that inhibition of JunB could repress tumor growth and angiogenesis, suggesting that JunB may be an oncogene in ccRCC." (PMID 37731821, 2023). "Although AP-1 proteins are thought to be carcinogenic, current research has discovered that JunB and c-Fos have tumor-suppressing activity, providing insights into the molecular processes that control the oncogenic and anti-oncogenic functions of AP-1 in tumorigenesis." (PMID 35664945, 2022). "The fact that we observed JUNB-dependent repression of TGFB2 in the experiments presented above led us to wonder about the possible disturbance of TGFB2 downstream signaling in JUNB-overexpressing tumor cells growing in a TGFB2-rich environment." (PMID 36494864, 2022). "JunB knockdown and knockout limited the progression of tumor migration and invasion, suggesting that the downregulation of JunB expression might be a potential therapeutic strategy for inhibiting distant metastasis in patients with HPV-driven cancer." (PMID 36479105, 2022). "Besides, activated AP-1 with robust c-Jun and JunB overexpression was found in all tumor cells of patients with HL." (PMID 35211408, 2022). "The results suggested that JUNB was upregulated in tumor tissues and the low immunity score group." (PMID 35812726, 2022). "Thus, our data point to novel functions for JUNB in the control of both normal cell cycle and tumor aggressiveness." (PMID 36494864, 2022). "However, the understanding of the molecular roles of JUNB in tumor cell proliferation and expansion remains ill-defined." (PMID 36494864, 2022). "Thus, taken together, our data indicate that JUNB overexpression in U2OS cells promotes both tumor development and metastasis in vivo." (PMID 36494864, 2022). "Our results reveal novel functions for JUNB in cell proliferation and tumor aggressiveness through regulation of cyclin E1 and TGF-β2 expression, which might be exploited for cancer prognosis and therapy." (PMID 36494864, 2022). "Moreover, our results suggest that JunB-induced generation of AFs is dependent on the molecular background of tumor cells." (PMID 34007044, 2021). "As JUNB levels are tightly controlled and JUNB is hardly expressed in adjacent non-tumor tissue, we wondered whether this high stromal JUNB expression might impact the metastastic spread." (PMID 34282521, 2021). "In line with a previous study, in the tumor blood and lymphatic vascular density as well as primary tumor growth were not affected by JUNB loss." (PMID 34282521, 2021). "Three primary tumor samples revealed low expression of JUNB (H-scores 5, 6, and 9)." (PMID 31370904, 2019). "Furthermore, in one patient with available primary tumor and metastasis, JUNB was dramatically increased (from H-score 0 to H-score 120) in metastatic tissue, denoting the critical role of this molecule in cancer progression." (PMID 31370904, 2019).
tumor (continued). "Notably, TPA, a tumor-initiating agent, strongly induced hyperplasia not only in the epidermis but also in sebaceous glands of JunB cKO as compared to wild type mice, thus confirming its anti-proliferative, possibly tumor suppressing effects." (PMID 30143626, 2018). "JunB has been described as a tumor suppressing protein in earlier reports." (PMID 30143626, 2018). "The knockdown and knockout of JunB reduced tumor migration and invasion in vitro as well as lung metastasis in vivo, suggesting that the JunB pathway might be a useful a therapeutic target for inhibiting distant metastasis in patients with HNSCC." (PMID 26754630, 2016). "Further studies are required to examine the details of the cellular and molecular mechanisms of the promotion tumor invasion by JunB in metastatic HNSCC in order to identify specific JunB inhibitors and demonstrate their efficacy in inhibiting tumor invasion and metastasis in HNSCC." (PMID 26754630, 2016). "In contrast, JunB acts as a context-dependent tumor suppressor." (PMID 26398940, 2015). "Previously, JUNB was shown to act as a critical positive regulator of blood vessel development and homeostasis as well as a negative regulator of proliferation, inflammation and tumour growth." (PMID 26458334, 2015). "Another example of a gene that is primarily up regulated by STAT3 but may support or suppress tumor growth is JunB." (PMID 24743777, 2014). "IHC on FFPE tissue sections of the same tumor samples revealed equal JUNB expression patterns." (PMID 25013898, 2014). "The expression of TAPBPL, SERPINB9, RCAN1, TMBIM4, JUNB, IL4R, and LY75 is significantly up-regulated in tumor samples with their high expression associated with a poor outcome; the expression of MGST3 is down-regulated in tumor samples with its low expression associated with poor prognosis." (PMID 25133526, 2014). "Moreover, expression of dominant-negative JunB in this model, which inhibits JunB function, increases tumor formation." (PMID 23762562, 2013). "The gradual but distinct increase in JunB protein expression after berberine treatment strongly support the tumor suppressor activity of JunB as it was earlier reported that JunB and JunD can negatively regulate cell proliferation and has an opposite effect on gene expression." (PMID 21496227, 2011). "However, JUNB expression was lower in cells cultured in the 3LBNC scaffold compared to standard well plates, suggesting that the scaffold recapitulates aspects of the tumor microenvironment that influence the fine-tuned regulation of gene expression." (PMID 40558895, 2025). "Given that JunB had a role in promoting cell invasion and angiogenesis in VHL-deficient RCC, we hypothesize that a close association between this CAFs cluster and tumor invasion." (PMID 38292868, 2024). "In HNSCC, knockout or knockdown of JunB could inhibit tumor cell migration and invasion in vitro, and repress distant lung metastasis in vivo, suggesting JunB may be an oncogene in HNSCC progression, but more studies are necessary to be performed to support this point." (PMID 37731821, 2023). "In addition, since JunB is an important determinant of immune cells fate and regulates the secretion of inflammatory cytokines, it is an interesting question whether JunB can promote the anti-tumor effect of immune cells in PCa." (PMID 37731821, 2023). "Finally, it is possible that other extracellular cues besides TGFB2 provided by the tumor environment might affect JUNB signaling in cancerous cells and, thereby, their tumorigenicity." (PMID 36494864, 2022). "Moreover, CAFs showed a pro-tumor proliferation effect via JUNB as suggested by the CCK-8 assay." (PMID 35812726, 2022). "In addition, CAFs showed a pro-tumor proliferation effect via JUNB." (PMID 35812726, 2022). "Hence, elevated myeloid recruitment in JUNB KO mice was not caused by increased granulopoiesis but is specifically induced by the primary tumor." (PMID 34282521, 2021).
tumor (continued). "Therefore, we assessed whether JunB may also suppress epidermal hyperproliferation essential for tumor initiation." (PMID 30143626, 2018). "Thus, PDK1 functions as a tumor promoter in human GBC by upregulating JunB." (PMID 26318166, 2015). "Between ARGs_High tumour cells and T cells, ITGB2-ICAM1 and TGFB1-TGFBR1 were ligand-receptor pairs with strong regulatory potential, while EDN1, JUNB, SOCS3, VIM and COL1A2 were top genes target to TGFB1." (PMID 40830065, 2025). "The inactivation of SRSF1 in tumor cells reduces transcription factors, including c-Jun, c-myc, and JunB, facilitating glycolytic metabolism reprogramming, which restores CD8+ T cell function and inhibits tumor growth." (PMID 39837814, 2025). "NAT10 induces glycolysis and immunosuppressive tumor microenvironment by upregulating the upstream genes of glycolysis such as FOXP1 and JunB by stimulating ac4C modification of their mRNAs." (PMID 40588654, 2025). "ATAC-, ChIP-, and RNA-seq analyses reveal that JUNB/AP1- and HDAC-mediated epigenetic programs repress pro-inflammatory signatures in tumor cells, antagonizing cJUN/AP1 signaling, favoring a therapy-responsive classical neoplastic state." (PMID 39762215, 2025). "In addition, because JUNB expression in epithelial HCCs is related to fibrosis, apoptosis, and angiogenesis in addition to cancer metastasis, it might be involved in the immune environment in tumor tissue." (PMID 40253402, 2025). "The localization of JUNB in primary tumors of human HCC with lung metastasis was also similar to that in mouse subcutaneous tumors, with many positive cells near the tumor nodule." (PMID 40253402, 2025). "In contrast, the ED analysis revealed 204 TFs, with 30 showing substantial tumor-specific TFBS enrichment, including TP63, FOSL1, JUND, JUNB, and KLF5, underscoring their potential roles in tumorigenesis." (PMID 41323280, 2025). "This showed higher age, neoadjuvant therapy, higher pT-, higher pN-stages, vascular invasion, tumor grade, regression, HER2/neu positivity as well as positive JUNB staining significantly correlated to poor overall survival." (PMID 40701988, 2025). "In this process, KRAS mutation stabilizes the key oncogenic activator protein 1 (AP-1) TFs (JUNB and FOSL1), locking the progenitor state to initiate tumor development." (PMID 40032852, 2025). "JUNB and JUND are credited with both tumor-suppressing and oncogenic roles, since the outcome of their activation relies on the specific cancer type, disease stage, intracellular localization, and the expression of interacting cofactors." (PMID 41020863, 2025). "The peri-necrotic zone and pseudo-palisading cells around necrosis showed significantly higher mRNA levels of JUN, JUNB, FOS, and FOSL2 compared to other regions of the tumor, such as the leading-edge, infiltrating tumor, and cellular tumor." (PMID 39257581, 2024). "Results showed that the regulatory factors CRNDE, EDN1, JUNB, and MAP2K1/2, ZFP36 mainly regulate differentially expressed genes (VEGFA, EGFR, PLAUR) to regulate invasion of cells, invasion of tumor, and microtubule dynamics." (PMID 38711992, 2024). "While JUND and JUNB demonstrate tumor-suppressive activity, JUN and FOS frequently display oncogenic characteristics when acting as either tumor suppressors or oncogenes in cancer." (PMID 38674385, 2024). "SIK1, a serine/threonine kinase, regulates the cell cycle and gluconeogenesis and acts as a tumor suppressor; SPAG4 and JUNB regulate cell proliferation and differentiation." (PMID 39025980, 2024). "The andrographolide can inhibit tumor growth and invasion of NSCLC by upregulating HLJ1, a novel tumor suppressor, through activation of JUNB." (PMID 39712244, 2024). "Importantly, disrupting the signaling between ERK2 and JUNB and Fos related antigen-1 transcription factors enabled vemurafenib-addicted tumor cells to survive on treatment discontinuation, suggesting the involvement of these transcription factors in developing tumor cell addiction to vemurafenib." (PMID 37834284, 2023).
tumor (continued). "The most five active regulators were identical in tumor and normal tissues, SPI1, CEBPB, JUNB, FOS, and KLF4." (PMID 37335089, 2023). "Together, our results indicated that ZIC2 induced M2 phenotype polarization of TAMs by regulating JUNB and MCSF in vivo, contributing to tumor development." (PMID 37479694, 2023). "Fto knockdown suppress the expression of transcription factors c-Jun, JunB, and CEBPB, restores the function of CD8+ T cells by impairing the glycolytic activity of tumor cells, thereby inhibiting tumor growth." (PMID 35672673, 2022). "Factors released from tumor cells feed forward to increase activation of NF-κB (NF-κB1), STAT3, and AP1 (JUN, JUNB, and FOS) in surrounding cells." (PMID 36134665, 2022). "At the late phase, R-Smad is redirected to the promoters of a set of invasion genes via a cooperation with JUNB, thus suggesting a role of sustained TGF-β signaling in favoring a tumor-promoting outcome." (PMID 35794621, 2022). "Upregulated within the tumor-infiltrating CD4+ T cells were heat shock proteins (HSPA1A and HSPA1B), Jun and FOS constituents (FOS, JUN, and JUNB), MHC-II molecules (HLA-DRB), and secreted molecules (CCL5, GZMA, and GZMK)." (PMID 33504936, 2021). "To exclude the possibility that enhanced myeloid cell infiltration in JUNB-deficient mice is not tumor-induced but rather a result of enhanced granulopoiesis, we investigated the expression of immune cell markers by RT-qPCR in lungs of tumor-bearing and age-matched unchallenged mice." (PMID 34282521, 2021). "Our results showed that the relative mRNA expression of ADIRF, MT2A, MT1M, and JUNB was downregulated after TGF-beta treatment and/or tumor stimulation, while the expression level of C11orf96 was upregulated, even after tumor stimulation." (PMID 33777046, 2021). "Although, AP-1 proteins are primarily considered to be oncogenic, recent studies revealed that JUNB and c-FOS proteins display a tumor-suppressor activity as well." (PMID 32296574, 2020). "The expression of SOCS3, JUNB, and ZFP36 is highly correlated in PCa, and through immunohistochemical analysis we found SOCS3, JUNB, and ZFP36 proteins were mainly expressed in PCa epithelial cells with a small amount in tumor stroma." (PMID 32951005, 2020). "Whilst c-Jun oncoprotein seems to drive proliferation and migration in human cancers, at the same time, there are Jun (JunB and JunD), Fos and ATF proteins that have been suggested to exert tumor suppressor function." (PMID 33202877, 2020). "In general, c-JUN acts as an oncogenic driver, whereas JUNB and JUND have tumour suppressive effects." (PMID 29597249, 2018). "TGF-β1 can promote CCR7/CCL21-mediated crosstalk between tumor cells and LECs, and increase CCR7 expression in EMT cells through p38 mitogen-activated protein kinase (MAPK)-mediated activation of the JunB transcription factor." (PMID 28036019, 2016). "The tumor suppressor network in which p73 appears to be a participant involves E2F1, JunB, INK4a/p16, ARF/p19, p57kip2 and BRCA1." (PMID 17407586, 2007). "The tumor suppressor pathway in which p73 appears to be a participant involves E2F1, JunB, p16, p19, p57kip2 and BRCA1." (PMID 17407586, 2007). "Furthermore, transcription factors FOS and JUNB showed robust correlations with CXCL2 and HBEGF, suggesting multiple molecular mechanisms regulating tumor angiogenesis in Transitional Mono to M0 cells." (PMID 41514936, 2026). "Several studies (of prostate and non-prostate origin) converge that JUND, similarly to JUNB, displays both tumor promoter and tumor suppressor activities regarding several factors, including the cancer type, cellular context, and cooperation with other TFs." (PMID 41020863, 2025). "NAT10 also upregulates JunB expression by increasing ac4C modification levels on its mRNA, which further upregulates LDHA expression and facilitated glycolysis and the immunosuppressive properties of tumor-infiltrating regulatory T cells." (PMID 40588654, 2025).